FNDC10 (fibronectin type III domain containing 10)
Synonyms: C1orf233
Tractability: Antibody: UniProt predicts a signal peptide or a membrane-spanning region.
Gene: Protein-coding gene on chromosome 1 (1,598,012 to 1,600,135, reverse strand). Ensembl gene ENSG00000228594.
Subcellular location: Membrane
Gene Ontology:
Cellular component: membrane
Genetic constraint (gnomAD): Loss-of-function variants: 7 observed, 5.45 expected, observed/expected ratio (o/e) 1.28, 90% interval 0.7 to 1.89. That is too few expected variants to judge how well the gene tolerates losing a copy. Missense variants: 271 observed, 239.09 expected, observed/expected ratio (o/e) 1.13, 90% interval 1.03 to 1.25. Synonymous variants: 163 observed, 120.93 expected, observed/expected ratio (o/e) 1.35, 90% interval 1.19 to 1.53.
Homologues: Orthologues: chimpanzee FNDC10 (99% identical), macaque FNDC10 (97% identical), pig FNDC10 (91% identical), rat Rps15al2 (85% identical), mouse Fndc10 (83% identical), guinea pig Fndc10 (67% identical), tropical clawed frog fndc10 (51% identical), zebrafish fndc10 (40% identical).
Diseases named in the same sentence as FNDC10 in open-access papers:
FNDC10 is named in the same sentence as 1 disease in open-access papers, as found by Europe PMC text mining. Sharing a sentence is not in itself a finding about the gene and the disease.
FNDC10 shares sentences with these, for which no sentence is quoted: atherosclerosis (1 paper).